AASS (aminoadipate-semialdehyde synthase)
Description:
Bifunctional enzyme that catalyzes the first two steps in lysine degradation.
Synonyms: LORSDH; LKRSDH; LKR/SDH
Tractability: Small molecule: a structure with a bound ligand is known. PROTAC: ubiquitination databases record sites on it; its protein half-life has been measured.
Gene: Protein-coding gene on chromosome 7 (122,064,583 to 122,144,489, reverse strand). Ensembl gene ENSG00000008311.
Subcellular location: Mitochondrion
Subcellular location (Human Protein Atlas): Mitochondria; Nucleoplasm; Vesicles
Pathways (Reactome):
Metabolism: Lysine catabolism
Gene Ontology:
Molecular function: saccharopine dehydrogenase (NAD+, L-glutamate-forming) activity; saccharopine dehydrogenase (NADP+, L-lysine-forming) activity; histone binding; saccharopine dehydrogenase (NAD+, L-lysine-forming) activity; transcription corepressor activity
Biological process: L-lysine catabolic process; negative regulation of transcription by RNA polymerase II
Cellular component: mitochondrion; cytosol; mitochondrial matrix; nucleus
Genetic constraint (gnomAD): Loss-of-function variants: 78 observed, 99.35 expected, observed/expected ratio (o/e) 0.79, 90% interval 0.65 to 0.95. The upper end of that interval is the gene's LOEUF score, 0.95, which puts it in group 4 of 6, group 1 being the genes least tolerant of losing a copy. Missense variants: 1,018 observed, 1,158.7 expected, observed/expected ratio (o/e) 0.88, 90% interval 0.83 to 0.93. Synonymous variants: 371 observed, 405.11 expected, observed/expected ratio (o/e) 0.92, 90% interval 0.84 to 1.
Gene-disease validity (ClinGen):
ClinGen rates the evidence that AASS causes each of these diseases.
hyperlysinemia (autosomal recessive): Definitive. Hyperlysinaemia is a lysine metabolism disorder characterized by elevated levels of lysine in the cerebrospinal fluid and blood.
Homologues: Orthologues: chimpanzee AASS (99% identical), macaque AASS (98% identical), rabbit AASS (93% identical), pig AASS (92% identical), dog AASS (89% identical), guinea pig AASS (88% identical), mouse Aass (87% identical), rat Aass (87% identical), tropical clawed frog aass (73% identical), zebrafish aass (66% identical), Drosophila melanogaster LKRSDH (51% identical), Caenorhabditis elegans aass-1 (48% identical).
Diseases named in the same sentence as AASS in open-access papers:
AASS is named in the same sentence as 26 diseases in open-access papers, as found by Europe PMC text mining. Sharing a sentence is not in itself a finding about the gene and the disease. The quoted sentences say what the papers report.
hyperlysinemia (9 papers, 2013 to 2025). "In this work, we proposed a probiotic cocktail strategy by engineering two cascade metabolic bacteria to treat hyperlysinemia, an inherited lysine metabolic disorder with loss of α-aminoadipate semialdehyde synthase (AASS) activity." (PMID 38873158, 2024). "Hyperlysinemia is a rare autosomal recessive deficiency of 2-aminoadipic semialdehyde synthase (AASS) affecting the initial step in lysine degradation." (PMID 37927488, 2023). "Hyperlysinemia caused by AASS deficiency due to mutations in AASS (MIM 238 700), is currently regarded as a biochemical phenotype of questionable clinical significance." (PMID 36128717, 2022). "In two patients originating from one family, the hyperlysinemia was caused by a contiguous gene deletion syndrome affecting AASS and PTPRZ1." (PMID 23570448, 2013). "We conclude that in our cohort of 8 cases, hyperlysinemia is caused by mutations in the AASS gene." (PMID 23570448, 2013). "Lysine accumulation, known as hyperlysinemia type I, is caused by an impairment in the activity of the LKR domain of the AASS gene." (PMID 41194801, 2025). "Hyperlysinemia in humans has been associated with the p.R65Q, p.A154T and p.L419R variants in the LOR domain of AASS." (PMID 36128717, 2022). "Hyperlysinemia is an autosomal recessive disorder resulting from defects in the AASS gene." (PMID 40710547, 2025). "Metabolic features of the subject initially indicated familial hyperlysinemia (hyperlysinemia, type I; 7q31.32; MIM 238700), which is caused by a mutation in the AASS gene (7q31.32; MIM 605113), which subsequently was ruled out in order to consider other possible etiologies." (PMID 32916978, 2020).
glutaric aciduria type I (3 papers, 2022 to 2025). "Moreover, AASS is a unique drug target for inborn errors of metabolism such as glutaric aciduria type 1 that arise from deficiencies downstream in the lysine degradation pathway." (PMID 36128717, 2022).
epilepsy (2 papers, 2016 to 2020). A brain disorder characterized by episodes of abnormally increased neuronal discharge resulting in transient episodes of sensory or motor neurological dysfunction, or psychic dysfunction. "We have also isolated ligands 8 and 9 which bound tightly to AASS (alpha‐aminoadipic semialdehyde synthase), an enzyme involved in the major lysine degradation pathway implicated as therapy for pyridoxine‐dependent epilepsy (PDE)." (PMID 33240760, 2020). "Similarly, Patients B6 and B7 had mutations in AASS, which would explain the hyperlysinaemia seen in both plasma and CSF but not the presence of developmental delay, microcephaly, hypotonia and epilepsy." (PMID 27604308, 2016).
breast carcinoma (1 paper, 2026). "Aminoadipate–semialdehyde synthase (AASS) is involved in amino acid metabolism and can influence responses to asparaginase and corticosteroids (both used in ALL treatment); otherwise, altered AASS expression has also been seen in breast cancer." (PMID 41379638, 2026).
cholera (1 paper, 2020). "Our group recently discovered another AasS from the gram-negative bacterium Vibrio cholerae (VcAasS), the causative agent of the disease cholera (unpublished data)." (PMID 33082446, 2020).
diabetes (1 paper, 2023). "AASS encodes the enzyme aminoadipate-semialdehyde synthase, which is involved in mammalian lysine degradation and in hyperlysinaemia, but which has not yet been characterised in the context of impaired glucose metabolism, insulin resistance or diabetes." (PMID 36790478, 2023). "Of the 15 top candidate genes, ST3GAL2, AASS, ARF1 and the transcription factor SIN3A are novel candidates for predicting a refined diabetes risk and intervention response." (PMID 36790478, 2023).
hyperlysinemia type II (1 paper, 2025). "The same cannot be said in the case of accumulation of saccharopine, as a mutation in the SDH domain of AASS leads to hyperlysinemia type II or saccharopinuria, a mild symptomatic disease that, in some cases, can lead to detrimental neurological dysfunction, retardation, and brain malfunction." (PMID 41194801, 2025).
lipoma (1 paper, 2014). A benign, usually painless, well-circumscribed lipomatous tumor composed of adipose tissue. "Hsa-miR-532-5p regulates lipoma preferred partner (LPP), an indispensable regulator of migration, and the aminoadipate-semialdehyde synthase (AASS) gene, involved in lysine degradation pathway." (PMID 24866763, 2014).
metastatic tumors (1 paper, 2021). "DIRAS1, FBXL16, TP53I11, TFF2, and ZNF467 were upregulated in both metastatic tumors and GHSROS-overexpressing PC3 and LNCaP cells, while AASS, CHRDL1, CNTN1, IFI16, and MUM1L1 were downregulated." (PMID 33585078, 2021).
osteosarcoma (1 paper, 2023). A usually aggressive malignant bone-forming mesenchymal neoplasm, predominantly affecting adolescents and young adults. "HSPB8/RHD/AASS/NFASC has not yet been found to be associated with osteosarcoma." (PMID 36983630, 2023). "HSPB8, RHD, AASS, and NFASC were genes we identified that have not been previously reported to be associated with osteosarcoma." (PMID 36983630, 2023).
cancer (4 papers, 2015 to 2021). A tumor composed of atypical neoplastic, often pleomorphic cells that invade other tissues. "While AASS controls the first two steps in the lysine degradation pathway, lysine modification takes part in the transcript regulation reported in the pan-cancer analysis." (PMID 33517886, 2021). "To validate the prediction that activating these enzymes may help reduce cancer cell growth, we over-expressed two related genes, AASS and AADAT, in a series of cancer cell lines with different tissues-of-origin and genetic backgrounds." (PMID 31601242, 2019). "The cancer gene expression database analysis showed that the expressions of vesicle regulator P4HA2 were increased in seven out of 33 tumor types compared with controls; and the expression of vesicle regulator AASS in seven out of 33 tumor types was decreased compared with that of controls." (PMID 34368262, 2021).
tumor (3 papers, 2013 to 2021). "Subsequently, we confirmed well-characterized oncogenes among tumor-related loci (such as EGFR and KIT) and detected novel genes that gained chromosome sequences (such as AASS, HYAL4, NDUFA5 and SPAM1) in both LGG and HGG." (PMID 23451178, 2013). "We similarly identified certain molecules such as alpha‐aminoadipic semialdehyde synthase (AASS) and coenzyme Q 7 homolog ubiquinone (COQ7) whose functions were unknown in tumor cells." (PMID 31025554, 2019).
AASS also shares sentences with these, for which no sentence is quoted: alcohol dependence (1 paper); autism spectrum disorder (1); developmental delay (1); diabetic nephropathy (1); exudative vitreoretinopathy (1); genetic disease (1); histoplasmosis (1); infection (1); Insulin resistance (1); membranous nephropathy (1); microcephaly (1); pyridoxine-dependent epilepsy (1); renal disease (1); Type 2 Diabetes (1).